INS (insulin)
Diseases named in the same sentence as INS in open-access papers (continued):
Sharing a sentence is not in itself a finding about the gene and the disease.
Obesity (continued). "Xenin, an ancient regulatory peptide known as a regulator of insulin and glucagon secretion (thereby an important therapeutic target in DM and obesity), was also shown to be a factor of PCOS pathogenesis." (PMID 33920227, 2021). "The prepared nanoparticles significantly improved insulin sensitivity by modulating both innate and adaptive immunity, thus providing a novel avenue for the therapy of obesity-induced IR." (PMID 34138319, 2021). "Among the indicators related to obesity, BMI, waist circumference, insulin and IR were positively correlated with PV levels, while serum TT levels and SHBG were negatively associated with PV levels (P = 0.004 and P = 0.042, respectively)." (PMID 34239023, 2021). "As expected, the delivery of exosomes from lean ADSCs into obese mice produced desirable effects on relieving obesity and improving insulin sensitivity in these mice." (PMID 34108967, 2021). "Downregulation of insulin expression by insulin gene dosage, pharmaceutical suppression of insulin or fat cell specific insulin receptor knockouts protect against obesity." (PMID 33544739, 2021). "We used higher insulin infusion rate during the hyperinsulinemic clamp in the groups with obesity compared with the NW group." (PMID 33616083, 2021). "A study with a selective intestinal FXR inhibitor, Gly-MCA, demonstrated a reduction of triglyceride accumulation in the liver, decreased blood glucose levels and increased insulin sensitivity in the murine model of obesity." (PMID 34483922, 2021). "In the quest for effective control of obesity, four hormones were discovered to havea link; insulin, leptin, ghrelin and obestatin and the growth hormone secretagoguereceptor (GHS-R)." (PMID 34879109, 2021). "Associations between DII and HTGWCP were confirmed in Multinomial logistic regression to adjust for confounder points; energy intake, age, insulin plasma level, marital status, education, economic status and family history of obesity." (PMID 34399836, 2021). "An association of NSAID use and BMI has not been reported, but high dose salicylates can result in lower serum insulin and glucose in diet induced obesity models, which phenocopies the insulin and glucose profile of GKN1−/− mice." (PMID 33947892, 2021). "In spite of the unclarity of the causal relationship of these events, most studies have shown that the prevention of macrophage accumulation in adipose tissue improves insulin sensitivity in various animal models of obesity." (PMID 33926085, 2021). "Although VLCKD has been reported to efficiently reduce body weight, the levels of glycaemia, insulin, and glycated hemoglobin (HbA1c) in patients with overweight or obesity, its effects on β-cell function are less clear." (PMID 33063272, 2021). "Obesity is recognized as an insulin-resistant state characterized by low-grade chronic inflammation." (PMID 34884763, 2021). "When obesity develops during AAPs use, insulin sensitive tissues become more resistant to insulin and β-cells increase insulin secretion in order to compensate, which in the long term can determine β-cells deterioration thus increasing the risk of T2D." (PMID 33800403, 2021). "Heterozygous Kmt2d+/− mice demonstrated improved obesity, lipid accumulation, glucose tolerance, and insulin sensitivity." (PMID 34867780, 2021). "The chronic low-level inflammation within the adipose tissue in obesity results in oxidative stress, activation of inflammatory cytokines, deregulation of adipokines signaling, and increased circulating levels of insulin and insulin-like growth factors (IGF)." (PMID 33920379, 2021). "Genetic deletion of Th2 or M2 inducers increases the risk for metabolic disorders, and M2 macrophage infusion into obese mice has proven to be effective in treating obesity and improving insulin sensitivity." (PMID 34512555, 2021).
Obesity (continued). "Exercise increases fat oxidation responses in individuals living with obesity; however, limited research exists on the relationship between substrate oxidation and insulin sensitivity after sprint interval training (SIT)." (PMID 34110721, 2021). "In terms of mechanism and effects on brain physiology and maternal behavior, the effect of insulin treatment in pregnant females with obesity can also be modelled in a partially humanized mouse containing (and expressing) the human PL gene family." (PMID 33743677, 2021). "Supplementation of epigenetic diets would help enhance metabolic homeostasis by ameliorating processes involved in the pathophysiology of MetS, including inflammation, obesity, glucose intolerance and insulin insensitivity." (PMID 34068765, 2021). "The administration of recombinant FGF-21 in non-human models has been associated with an improved lipoprotein profile, increased glucose tolerance and insulin sensitivity, and reduced hepatic steatosis and obesity." (PMID 34822430, 2021). "In the result of aberrant metabolic functions, hyperglycemia increase, and insulin sensitivity decrease, consequently, stimulate additional inflammatory responses in obesity and promote obesity-induced metabolic disease T2D." (PMID 33924088, 2021). "Consistently, ubiquitous and moderate overexpression of Atg5 in mice, resulting in increased autophagy, leads to a leaner phenotype, an increased glucose tolerance and insulin sensitivity, and resistance to age-induced obesity." (PMID 34277603, 2021). "Although IR plays a central role in the complex pathogenesis of metabolic dysfunction and cognitive dysfunction in people who gain weight and develop obesity, the compelling data support an important effect of lifestyle factors on insulin sensitivity." (PMID 33430419, 2021). "One of the characteristic features of obesity and a forerunner of T2D is the reduced insulin sensitivity in skeletal muscle." (PMID 33904649, 2021). "We have recently shown that ablation of the serine protease kallikrein-related peptidase 7 (Klk7) specifically in adipose tissue preserves systemic insulin sensitivity and protects mice from obesity-related AT inflammation." (PMID 33572949, 2021). "Six-week administration of HSG4112 to HFD-induced obese mice led to dose-dependent normalization of obesity-related parameters, including body weight, muscle and adipose tissue weight, adipocyte size, and serum leptin/insulin/glucose levels." (PMID 32943760, 2021). "The co-twin-pairs share a similar genome at sequence level that enables us to study the effects of obesity and insulin resistance in conjunction with long-term exercise training without the confounding effects of genetic variation." (PMID 33627179, 2021). "In this study, the authors found a novel role of ACE2 in obesity, where ACE2 negatively regulated obesity-induced epicardial adipose tissue inflammation, cardiac insulin resistance, and alterations in cardiac metabolism." (PMID 34360741, 2021). "Taken together, our results revealed that knockdown of circRNF111 impairs insulin sensitivity and accelerates ectopic lipid deposition of obesity-induced metabolic syndrome via sponging miR-143-3p." (PMID 34485272, 2021). "In our data, aflatoxin-associated DMRs were enriched in inflammatory pathways and signalling events affecting the growth hormone-insulin-obesity axis, as well as Wnt signalling (involved in embryogenesis)." (PMID 34445674, 2021). "We investigated the prebiotic effect of 1-kestose supplementation on fasting insulin concentration in obesity-prone humans and rats." (PMID 34578862, 2021). "Since defective lipophagy is thought to have a role in the pathology of obesity with lipid breakdown, insulin sensitivity, and food intake, therefore, regulating lipophagy can be a therapeutic target for adiposity and obesity." (PMID 33505503, 2021).
Obesity (continued). "Till now, only a few adipokines display low levels in obesity, some having atheroprotective, anti-inflammatory and insulin-sensitizing properties such as adiponectin, the most well-known beneficial adipokine." (PMID 34638803, 2021). "Consistent with previous research, we found that HFD successfully induced mice obesity and related metabolic disorders, as indicated by increased fat deposition, insulin resistance, and hepatic steatosis." (PMID 35095784, 2021). "The present study clearly compared the effects of S‐inulin (DP: 2–9) and ML‐inulin (DP: 17–24) on HFD‐induced obesity, fatty liver, inflammation and insulin sensitivity." (PMID 34262707, 2021). "Adipocyte-specific ANT2-KO mice are protected from obesity-induced adipose tissue hypoxia and show improved metaflammation, insulin sensitivity, and glucose tolerance." (PMID 34676827, 2021). "Since the manipulation of these miRNAs has been shown to affect whole-body energy expenditure, glucose tolerance and insulin sensitivity in vivo, they represent potentially critical therapeutic targets for treating obesity and related metabolic complications." (PMID 34943849, 2021). "Several potential mechanisms linking obesity and cancer have been identified as for instance higher estrogen exposure, systemic low-grade inflammation, increased insulin and insulin-like growth factor expression or altered adipokines secretion." (PMID 33972642, 2021). "In a skeletal muscle‐specific Akt1 transgenic mouse, Akt1‐mediated growth of glycolytic muscle led to ameliorated obesity with improvement in insulin sensitivity and reductions in serum insulin and glucose." (PMID 34227742, 2021). "Obesity-induced insulin resistance provokes an adaptive expansion of β cell mass, which compensates by secreting increased amount of insulin." (PMID 34572101, 2021). "To determine the role of brown fat Dnmt3b in the regulation of diet-induced obesity, we further conducted a metabolic characterization of body weight, energy metabolism and insulin sensitivity in female D3bKO mice fed HFD." (PMID 34947856, 2021). "Strategies that can improve insulin sensitivity and glycemic control are used in the management of obesity-related T2DM." (PMID 34295259, 2021). "This relationship between insulin signaling and other CMD is supported by an estimated 61% of T2D cases simultaneously correlate with obesity, therefore making obesity a strong risk factor for the development of T2D." (PMID 34497507, 2021). "Many people, usually with obesity, are in a state of compensated IR, in which IR is balanced by increased blood insulin concentration, or hyperinsulinaemia." (PMID 34841432, 2021). "A mouse model of diet-induced obesity was used to study the relationship between PAI-1, obesity, and insulin in PAI-1 deficient PAI-1−/− and wild type (WT) mice." (PMID 33937363, 2021). "In obesity, elevated levels of insulin/IGF-1 and gastrointestinal peptides that act via their cognate GPCRs, e.g., neurotensin, enhance the crosstalk between insulin receptor and GPCR signaling pathways, leading to increased cellular proliferation." (PMID 34680216, 2021). "Genetic ablation of Rap1-GTPase shields against dietary obesity and imbalance of glucose, insulin, and leptin sensitivity, reduction in inflammation, and ER stress in the hypothalamus." (PMID 33669862, 2021). "TGF-1β release from WAT is enhanced in obesity and in response to insulin and inhibitors of TNF-α and IL-β and correlates BMI and adiposity." (PMID 34884217, 2021). "Undoubtedly, developing a drug specifically targeting P300 functions in the regulation gluconeogenic gene expression and insulin signaling is of importance in the treatment of T2D and obesity." (PMID 33672754, 2021). "Adipokines, insulin and insulin-like growth factor, sex hormone and the chronic inflammation state play critical roles in the vicious crosstalk between obesity and BC." (PMID 34350120, 2021).
Obesity (continued). "In obesity, the pathological accumulation of lipids in skeletal muscle and the low-grade inflammation impairs insulin signaling and tissue proper glucose uptake and utilization." (PMID 33919703, 2021). "Obesity has detrimental effects on β-cell, resulting in the reduction of insulin content, diminished capacity to secrete insulin in response to glucose, and increased β-cell apoptosis." (PMID 34183666, 2021). "Moreover, obesity and obesity-associated hypertension may be the result of insulin sensitivity." (PMID 34187508, 2021). "The activation of TLR4 by free fatty acids, elevated in obesity, generates proinflammatory signals and activation of NF-κB that inhibits the transmission of the insulin signal." (PMID 33520042, 2021). "Whole-body insulin sensitivity was ultimately impaired, accompanied by a chronic state of subclinical systemic inflammation, and the development of an array of obesity-related complications including CVD and cardiovascular mortality." (PMID 33815359, 2021). "On the other hand, it is known that insulin is the most important regulator in glucose and lipid metabolism, so insulin resistance is a distinctive feature of obesity, T2DM, and cardiovascular diseases." (PMID 33430470, 2021). "Ubiquitous deletion of PTP1B results in increased insulin sensitivity, improved glucose tolerance, and protection against diet-induced obesity, hence the development of redox-based strategies to stabilise PTP1B in an oxidised (and therefore inactive) state." (PMID 33893069, 2021). "This leaf has pharmacological effects such as glucose absorption, insulin secretion production, antioxidant and anti-inflammatory agent, antihyperglycemic and antihyperlipidemic activities, and obesity management." (PMID 34912543, 2021). "To follow up on this possibility, we describe here a new cross-sectional cohort of adults with obesity and/or T2D in whom we performed assays for methylated and unmethylated INS using banked serum samples." (PMID 33670079, 2021). "A systematic review of seven studies found that reduced carbohydrate load can reduce circulating insulin levels, improve hormonal imbalance and resume ovulation to improve pregnancy rates compared to usual diet in overweight and women with obesity." (PMID 34684505, 2021). "Interleukin-4 (IL-4) and IL-13 signaling via IL-4Rα regulates adipose tissue lipolysis, insulin sensitivity, and liver fibrosis in obesity." (PMID 34302121, 2021). "Previous studies have indicated that the progressive decline in insulin action with age can be attributed largely to gradual increases in the degree of relative obesity and the number of sites of fat deposition." (PMID 33795778, 2021). "Blood HDL cholesterol concentration was lower (p < 0.05), whereas blood uric acid, CRP, LDL cholesterol, triglycerides, triglyceride-to-HDL cholesterol ratio, glucose, insulin, and leptin concentrations were all higher (p < 0.05) in adolescents with obesity." (PMID 34682324, 2021). "Obesity and high levels of circulating NEFA were also causatively linked to hampered insulin sensitivity in cells and compensatory hyperinsulinemia." (PMID 34930403, 2021). "It is conceivable that immunometabolic imbalance due to dysregulated insulin/IGF and leptin signaling pathways underlie immunodeficiency and infection susceptibility in nutritional imbalance, including malnutrition and obesity." (PMID 34795562, 2021). "Systemic Mir181a2b2 KO blocks methotrexate (MTX)-mediated insulin sensitivity and visceral fat inflammation in diet-induced obesity." (PMID 33416495, 2021). "To further gauge the effects of HSG4112 on obesity, we investigated the expression levels of genes related to energy metabolism, leptin and insulin signaling, and inflammation." (PMID 32943760, 2021). "In further support, A. muciniphila supplementation in male mice attenuated HFD-induced obesity and inflammation and improved insulin signaling." (PMID 34436440, 2021).
Obesity (continued). "Endothelial dysfunction is linked to insulin-resistant states, including T2DM, obesity and metabolic syndrome." (PMID 34440804, 2021). "Summarized in various reviews, nutrient excess and obesity can lead to mitochondrial dysfunction, oxidative stress and also membrane and ER stress, which promotes impaired insulin signaling and increased inflammatory cytokine production." (PMID 34140596, 2021). "Physical activity must be recommended strongly as part of the intervention plan to SA children with overweight or obesity, due to its ability to reverse insulin resistance in skeletal muscles and lower fasting insulin levels." (PMID 34070381, 2021). "In mice with diet-induced obesity, a single dose of recombinant Fgf21 is sufficient to improve insulin sensitivity and glucose disposal, and chronic administration promotes body weight loss and reduced adiposity." (PMID 34023388, 2021). "This study investigated the effects of black soybean anthocyanin extract (BSAn) on obesity-induced oxidative stress, the inflammatory response, and insulin resistance in a coculture system of hypertrophied 3T3-L1 adipocytes and RAW264 macrophages." (PMID 34199668, 2021). "Lactobacillus rhamnosus Lb102 and Bifidobacterium Bf141 showed good results in the treatment of obesity and in metabolic syndrome, with a reduction in visceral fat and inflammation, and an improvement in glucose tolerance and insulin sensitivity." (PMID 33693024, 2021). "In particular, glutamate was found to be the metabolite with the highest bivariate correlation with body fat and insulin sensitivity in an American-Indian adolescent with obesity study." (PMID 35050149, 2021). "As blood insulin levels and BCS were slightly positively correlated (ρ = 0.37), it should be noted that Glu was positively associated with obesity in humans." (PMID 33509165, 2021). "Insulin-sensitive tissues (adipose tissue, heart, and liver) are significantly affected by obesity at biomolecular and functional levels." (PMID 34194325, 2021). "Although decreased tissue sensitivity to insulin is compensated by hyperinsulinemia, IR leads to obesity, hypertension, dyslipidemia, and finally the metabolic syndrome." (PMID 34557264, 2021). "There is a robust pool of evidence in humans which demonstrates the positive influence of exercise on obesity and insulin resistance." (PMID 34048478, 2021). "Despite being more insulin resistant, fKO mice with diet-induced obesity show normal glucose clearance that suggests that beta cell function is not altered by fKO." (PMID 34588527, 2021). "p.Pro113Gln can cause a range of metabolic symptoms, including obesity, T2DM, and high fasting insulin levels." (PMID 34764936, 2021). "In a retrospective cohort study Meshel reported similar risk factors for insulin therapy (GMD in previous pregnancy, pre-pregnancy obesity, and maternal age >30 y)." (PMID 33767671, 2021). "Notwithstanding a common phenotype of obesity there was heterogeneity between our subjects in other respects, for instance the insulin responses during the meal test and the GIR during the clamps, as well as the lowering effects on EGP." (PMID 33684170, 2021). "Adipose tissue resistance to the antilipolytic insulin effect is frequent in T2D, impaired glucose tolerance, and centripetal obesity." (PMID 33320449, 2021). "CP patients with severe obesity had significantly higher insulin levels (p < 0.001) compared to normal-weight and obese CP patients." (PMID 33459867, 2021). "To test the influence of combined downhill running training and dietary fat regulation on obesity and insulin sensitivity, we examined body weight, adipose tissue weight, and change in GLUT4 protein content following the 8-week treatment period." (PMID 34177606, 2021). "Obesity is characterized by the accumulation of excessive adipose tissues in the body, leading to energy imbalance, alteration of appetite hormones, and insulin resistance." (PMID 34889899, 2021).